NFKB1 (nuclear factor kappa B subunit 1)
Diseases named in the same sentence as NFKB1 in open-access papers (continued):
Sharing a sentence is not in itself a finding about the gene and the disease.
Obesity (857 papers, 2006 to 2026). Accumulation of substantial excess body fat. "The objective of this study was to explore the potential biologic interaction between the NFKB1–94ins/delATTG promoter polymorphism and obesity in relation to the risk of incident ACS." (PMID 23671649, 2013). "Furthermore, we wanted to explore the potential interaction with obesity and the NFKB1 -94 ATTG ins/del polymorphism, respectively." (PMID 22768033, 2012). "RR* with 95% confidence interval in brackets for the combined effect of general obesity and the NFKB1-94ATTG polymophism in relation to acute coronary syndrome." (PMID 23671649, 2013). "By establishing a gene interaction network, we found that certain TFs (RELA and NFKB1) and miRNAs (has-miR-195-5p and has-miR-106a-5p) may play key roles in the development of obesity and GC." (PMID 39011399, 2024). "We hypothesized that polymorphisms in genes involved in the hypothalamic IKKβ/NF-κB signaling pathway (NFKB1, IKBKB, and SOCS3), alone or in interaction with nutrients, are associated with energy imbalance and obesity pathogenesis in humans." (PMID 30886629, 2019). "In this study, we investigated gene–gene and gene–environment interactions in the association between variants of three genes (NFKB1, IKBKB, SOCS3), macronutrient and alcohol intakes, and obesity-related phenotypes (BMI, alternative BMI cut-offs for East and South Asians, and waist circumference)." (PMID 30886629, 2019). "The variant allele of the NFKB1-94ins/delATTG promoter polymorphism did not substantially modify the association between obesity and incident ACS." (PMID 23671649, 2013). "Similarly, miR-126 had altered expression in obesity and may modulate CCL2 (chemokine ligand 2) through genes that encode ETS1, MAX, NFKB1, RELB, and STAT6 proteins." (PMID 36355127, 2022). "However, this study is the first to investigate gene–gene and gene–environment interactions between polymorphism in NFKB1, IKBKB, SOCS3, macronutrient and alcohol intakes, in the association between overnutrition and obesity-related phenotypes in human subjects." (PMID 30886629, 2019). "When we investigated the combined effect of SNP haplotypes 1, 2 and, 3 and obesity (BMI, WC adjusted for HC, HC adjusted for WC) or the NFKB1 -94 ATTG ins/del polymorphism, the results showed no indication that haplotype carrier status modified the effect of the investigated variable." (PMID 22768033, 2012). "In addition, variants near the NFKB1 gene have been associated to T2D based on the DIAGRAM dataset (best nearby SNP p-value = 1.6×10−5), while SMAD3 has been recently found to protect against diet-induced obesity as well as coronary artery disease." (PMID 23236286, 2012). "FXR1, NFKB1, and BACH1 are potent regulators of obesity-driven inflammation and metabolic dysfunction." (PMID 37698918, 2023). "Other nominally significant associations were established between WHOCS scales and: IFNL4 rs12979860, ACEIs, obesity, ARA-II, HCP5 rs2395029, ACE rs1799752, DPP4 rs17574, HMOX1 rs2071746, IL10 rs1800896, IL6 rs1818879, NFKB1 rs28362491, and MX1 rs469390." (PMID 35636966, 2022). "This analysis highlighted an increase in pro-inflammatory cytokines TNF-α and IL-6 and upregulation of NF-κB-related genes NFKB1 and RELA in obesity." (PMID 35215414, 2022). "Few studies have analysed NFKB1, RELA and MAPK1 mRNA expression in obesity." (PMID 35215414, 2022). "Furthermore, at T3, we observed reduced expression of key transcription factors NFKB1, FOSB, NCOR, CIITA with pregravid obesity (2-4 fold drop in leans vs. 4-6 fold drop in obese)." (PMID 34195568, 2021). "In addition, this study is one of the first to investigate gene–gene and gene–environment interactions between NFKB1, IKBKB, SOCS3 and macronutrient intakes on human and their effect on obesity-related phenotypes." (PMID 30886629, 2019).
hepatocellular carcinoma (856 papers, 2005 to 2026). A malignant tumor that arises from hepatocytes. "At the same time, NFKB1 plays an important regulatory role in aging-related chronic liver diseases, and its gene promoter polymorphisms increase the susceptibility of hepatocellular carcinoma to a certain extent." (PMID 30867448, 2019). "In addition, such a molecule would also activate NF‐κB in malignant or premalignant cells, which might prove detrimental; for example, Nfkb1−/− mice exposed to a chemical mutagen have accelerated development of hepatocellular carcinoma." (PMID 33480449, 2021).
pancreatic cancer (806 papers, 2003 to 2026). "Additionally, it was observed that translocation of NFκB1 into the nucleus is facilitated by Annexin A2 and subsequently leads to gemcitabine resistance in pancreatic cancer." (PMID 35896012, 2022). "Moreover, we revealed that nuclear factor kappa B 1 (NFκB1) was prominently upregulated in pancreatic cancer tissues and pancreatic CSCs, and NFκB1 was also identified as a direct target of miR-497." (PMID 35896012, 2022). "Thus, NFKB1 plays very contrasting roles in the development of colon and pancreatic cancers, and further research is needed to elucidate its cellular and context-dependent function." (PMID 30205516, 2018). "NFKB1 is distributed among several pathways in Module 4 involving the MAPK signaling pathway, chronic myeloid leukemia, pancreatic cancer, the Toll-like receptor signaling pathway, acute myeloid leukemia, T-cell and B-cell receptor signaling pathway and apoptosis." (PMID 20419126, 2010). "Curcumin was shown to suppress growth of bladder and pancreatic cancer cell lines through the inhibition of NFKB1-regulated proinflammatory and proproliferative gene products PTGS2 and CXCL8; both CXCL8 and PTGS2 were also found to be downregulated in pancreatic cancer." (PMID 34422220, 2021).
gastric cancer (777 papers, 2005 to 2026). A primary or metastatic malignant neoplasm involving the stomach. "We have demonstrated previously that NFKB1 single nucleotide polymorphism (SNP) rs4648068 GG homozygote was associated with the increased risk of gastric cancer in Chinese Han population." (PMID 25888547, 2015). "In the previous case–control study, we have demonstrated the role of NFKB1 rs4648068 polymorphisms in gastric cancer susceptibility in Chinese Han population." (PMID 25888547, 2015). "In this study, we have demonstrated that the NFKB1 polymorphism (rs4648068) is associated with the cell proliferation and motility in gastric cancer." (PMID 25888547, 2015). "The NFKB1 polymorphism (rs4648068) was found associated with the cell proliferation and motility in gastric cancer in this study." (PMID 25888547, 2015). "Our previous study indicated that NFKB1 polymorphism at intron region (rs4648068) was associated with increased risk of gastric cancer in Chinese Han population." (PMID 25888547, 2015). "This study investigated the possible association between the SNP polymorphisms of NFKB1 and susceptibility to gastric cancer and its tumor behavior." (PMID 22776619, 2012). "In this study, we have shown that people who carry the GG homozygous_genotype of the rs4648068 polymorphism in the NFKB1 gene appear to be at increased risk for developing gastric cancer." (PMID 22776619, 2012). "This study investigated the susceptibility of the rs4648068 A/G genotype in the intron region of NFKB1 to gastric cancer and the association of this polymorphism with clinicopathologic variables in gastric cancer patients." (PMID 22776619, 2012). "Therefore, we investigated the role of the NFKB1 rs4648068 polymorphism in gastric cancer susceptibility in the Han Chinese population in a case–control study." (PMID 22776619, 2012). "Several groups have shown that there is a relationship between gastric cancer and the polymorphisms of NFKB1 promoter regions, and local tumor growth and lymph node spread in gastric cancer have also been proven to be associated with N-myc downstream-regulated genes in previous reports." (PMID 22776619, 2012). "Finally, preliminary data suggested spontaneous gastric cancer in models of NFkappaB1 deficiency and recent papers suggested that significant proportion of CVID patients may harbor haploinsufficient NFKB1 mutations." (PMID 30455695, 2018). "Here the Nfkb1−/− mice display characteristics of gastric cancer in humans including T cell and NK cell infiltration, increased pro-inflammatory gene expression including IL-1β, IL-6, TNFα and osteopontin, and the metalloproteinases MMP-7, MMP-9 and MMP-13." (PMID 30205516, 2018). "Quantitative real-time PCR was used to detect NFKB1 SNP rs4648068 genotype in the patients with gastric cancer." (PMID 25888547, 2015). "In addition to these risk factors, we also recently demonstrated that genetic variability in specific genes (e.g., MUC2, NFKB1 and CD14) is associated with the progression to gastric cancer from precursor lesions." (PMID 34199386, 2021). "Unexpectedly, NFKB1 inhibited luciferase activity driven by F1100 in HGC-27 cells but slightly increased luciferase activity driven by F1100 in SGC7901 cells, suggesting that NFKB1 regulates FOXS1 expression in a manner dependent on the type of gastric cancer cells." (PMID 30918291, 2019). "Therefore, network pharmacology and molecular docking analyses revealed that dehydroxy-isocalamendiol and spathulenol exert therapeutic efficacy on gastric cancer by multiple targets, NFKB1 and HIF1A, and pathways (MAPK, PD-L1 checkpoint, PI3K-Akt, Ras, and HIF-1 pathways)." (PMID 39816318, 2024). "This suggested that there might be correlation between NFKB1 genotypes and the gastric cancer clinicopathologic characteristics such as lymph node status and serosa invasion because of the different associations that were observed for the high-risk subsets and the low-risk subsets." (PMID 22776619, 2012).
gastric cancer (continued). "Albumin (ALB), B-cell lymphoma 2 (BCL-2), nuclear factor kappa B subunit 1 (NFKB1), hypoxia-inducible factor 1 alpha (HIF1A), and interleukin 6 (IL-6) had a higher expression in gastric cancer than in normal conditions." (PMID 39816318, 2024). "As important genes in the ‘Adipocytokine signaling’ pathway, NFKB1 and STATS were found, which are known to affect the immunity of gastric cancer." (PMID 36928437, 2023). "The basic expression and functional role of NFKB1 and RELA (components of canonical NF-κB pathway) in gastric cancer (GC) have not been well elucidated." (PMID 26801246, 2016).
melanoma (759 papers, 2003 to 2026). A malignant, usually aggressive tumor composed of atypical, neoplastic melanocytes. "Recent studies in melanoma have indicated that some components of the PI3K pathway (PTEN, MTOR, IRS4, PIK3R1, PIK3R4, PIK3R5 and NFKB1) are co-mutated in 17% of BRAF V600E mutant and 9% of NRAS mutant melanomas." (PMID 23006971, 2012). "Moreover, depletion of NFKB1 in amoeboid melanoma cells reduced Myosin II activity, secretory potential and macrophage polarization." (PMID 30712866, 2019). "Our results show that, similarly to PIK3R2, NFKB1 gene expression is down-regulated by D6 in melanoma cells (FC = 0.47), but it is unclear whether this could be due to the PI3K/Akt signalling repression." (PMID 23642048, 2013). "Importantly, MLC2 and NFKB1 depletion in melanoma cells resulted in decreased CD206 in macrophages." (PMID 30712866, 2019). "Marked downregulation of expression of TREM1 and known TREM1 target genes (NFKB1, CCL20, IL6, and CXCL8) was determined in melanoma PDX models treated with VJDT." (PMID 37651197, 2023).
glioma (758 papers, 2007 to 2026). A benign or malignant brain and spinal cord tumor that arises from glial cells (astrocytes, oligodendrocytes, ependymal cells). "Additionally, nuclear factor kappa B subunit 1 (NF-kB) is believed to be the primary cause of gliomas’ resistance to radiation therapy." (PMID 39795182, 2024). "NFKB1 -94ins/delATTG polymorphism is produced in association with an increased risk of glioma." (PMID 35154340, 2021). "Furthermore, NFKB1 has been implicated in glioma development and progression." (PMID 34646821, 2021). "A previous study has shown that the lncRNA SLC26A4-AS1 promotes NPTX1 transcriptional activity by recruiting NFKB1, thereby exerting antiangiogenic effects in glioma cells." (PMID 35879775, 2022). "Intriguingly, CHI3L1 binds to actinin alpha 4 (ACTN4) and NFKB1, and enhances the NF-κB signaling pathway by promoting the NF-κB subunit nuclear translocation in glioma cells." (PMID 36276655, 2022). "We found the set of transcription factors, including REST, E2F1 and NFKB1, that are most likely to regulate gene expression in multiple TADs, containing specific glioma-related genes." (PMID 34341417, 2021). "Subsequently, we evaluated the influence of NFKB1 expression on the prognosis of glioma patients." (PMID 35473609, 2022). "Thus, SLC26A4-AS1 enhanced the transcriptional activity of NPTX1 via recruiting NFKB1 and hence had an anti-angiogenic effect on the glioma cells." (PMID 34646821, 2021). "Another study that developed murine glioma models based on ATRX KO followed by mutant IDH1 overexpression described upregulated pro-inflammatory gene programs and Nfkb1 signaling as characterized by single cell RNAseq and ATAC-seq23." (PMID 38272925, 2024). "In glioma, YKL-40 binds NFKB1 to upregulate NF-kB signaling, whilst in epithelial cells, NF-kB suppresses miR-149-5p to upregulate YKL-40 following TLR2/3 activation and induction of TNF-α." (PMID 36614029, 2022). "The Pearson correlation analysis indicated that strong positive correlations occurred between CHI3L1 and ACTN4, NFKB1 or NFKB2 in TCGA and CGGA glioma cohorts." (PMID 36276655, 2022). "For instance, SLC26A4-AS1 recruits NFKB1 to promote NPTX1 transcription, which exerts anti-angiogenic effects on glioma cells." (PMID 34803608, 2021). "Moreover, we identified a set of TFs which putatively regulate gene expression in multiple TADs, including known glioma related TFs such as REST, E2F1 and NFKB1." (PMID 34341417, 2021). "Higher expression of NFKB1 and SATB1, which are involved in regulating PD1 expression was only observed in patients with lower-grade gliomas." (PMID 34305618, 2021). "Additionally, silencing of NFKB1 or NPTX1 resulted in restoring the pro-angiogenic and aggressive features of the glioma cells, which had been inhibited by SLC26A4-AS1 expression." (PMID 34646821, 2021).
Hyperglycemia (667 papers, 2006 to 2026). An increased concentration of glucose in the blood. "Hyperinsulinaemia in either the presence or the absence of hyperglycaemia induced enhanced mRNA levels of all measured genes (Pinsu < 0.05), except for NFKB1 (Pinsu = 0.09) and TNF (Pinsu = 0.16)." (PMID 18290856, 2008). "Despite this, mRNA levels of the proinflammatory genes IL1A and CCL3 were also lower, and NFKB1 was also not up-regulated after hyperglycaemia." (PMID 18290856, 2008).
rheumatoid arthritis (614 papers, 2005 to 2026). A chronic, systemic autoimmune disorder characterized by inflammation in the synovial membranes and articular surfaces. "Conversely, an influence of NFKB1 signaling pathway polymorphisms on the development of cardiovascular events in patients with rheumatoid arthritis has been observed." (PMID 27965977, 2016). "Pathological activation of Nfkb1 may be involved in the development of various inflammatory and rheumatic diseases, such as osteoarthritis and rheumatoid arthritis in the bone." (PMID 32395748, 2020). "We predicted miRNAs with regulatory impact on NFKB1 and TRAF6 gene expression and selected the miR-194-5p, miR-124-3p, miR-9-5p, and miR-340-5p and their target genes for expression analyses on CD14+ monocytes from rheumatoid arthritis (RA) patients and healthy controls." (PMID 39058384, 2024).
ovarian carcinoma (593 papers, 2004 to 2026). A malignant neoplasm originating from the surface ovarian epithelium. "Polymorphisms in the NFKB1 gene have been suggested as risk factors for the development of several cancers including liver, gastric and ovarian cancers." (PMID 30205516, 2018). "Within ovarian cancer proliferation, low expression of miR9 promotes NFκB1 expression enhancing NFκB activity." (PMID 41459064, 2025). "Bioinformatics analysis demonstrated that EGCG affects NFκB1, Bcl-2, HIF-1α, MMP, etc., thereby reducing the risk of ovarian cancer." (PMID 41487287, 2025). "ANXA4 was found to bind NFKB1/p50 protein and to activate NF-κB signaling pathway in ovarian carcinoma." (PMID 38417630, 2024). "That finding is just in line with present results that NFκB1 was highly expressed in ovarian cancer and positively regulated by LINC00494 as its target gene." (PMID 33585183, 2020). "More importantly, inhibition on migration and invasion of ovarian cancer cells triggered by downregulated LINC00284 is reportedly dependent on the recruitment of NFκB1 and reduced expression of mesoderm-specific transcript." (PMID 33585183, 2020). "Our work demonstrated that LINC00494 promoted ovarian cancer progression by modulating FBXO32 via binding with the transcription factor NFκB1." (PMID 33585183, 2020). "LINC00494 and NFκB1 were highly expressed whereas FBXO32 had low expression in ovarian cancer cells and tissues." (PMID 33585183, 2020). "In HEK-293 cells and ovarian cancer ES-2 cells, NFκB1 has been shown to be a direct target of miR-9 by luciferase assay." (PMID 24373626, 2013). "In ovarian cancer, miR-9-5p has been demonstrated to act as a tumor suppressor microRNA by targeting the NF-κB family member NFκB1/p50." (PMID 24358187, 2013). "Therefore, we performed this study to define better the regulatory role of the LINC00494/NFκB1/FBXO32 axis in the development of ovarian cancer." (PMID 33585183, 2020). "In addition, overexpression of miR-9 led to downregulation of NFκB1 (P105/P50), consistent with previous data that NFκB1 was a direct target of miR-9 by translational repression in ovarian cancer cells." (PMID 24373626, 2013). "According to the results of the analysis of the relationship between the NFKB1 −94ins/del ATTG promoter polymorphism and subtypes of cancer, the NFKB1 −94ins/del ATTG promoter polymorphism is a risk factor for oral squamous cell carcinoma, ovarian cancer and nasopharyngeal carcinoma." (PMID 27463002, 2016). "Moreover, there might be a significant association with increased susceptibility between the NFKB1 −94ins/del ATTG promoter polymorphism and ovarian cancer, oral squamous cell carcinoma, and nasopharyngeal carcinoma." (PMID 27463002, 2016). "We performed real-time qPCR and immunoblotting analysis to determine the expression levels of LINC00494, NFκB1, and FBXO32 in several ovarian cancer cell lines (Caov-3, A2780, SKOV3, and CoC1) and a normal ovarian epithelial cell line, IOSE80." (PMID 33585183, 2020). "In this study, we found that LINC00494 can bind to the transcription factor NFκB1, and that NFκB1 then binds to the FBXO32 promoter, aggravating ovarian cancer." (PMID 33585183, 2020). "Bioinformatics analysis predicted potential interactions among LINC00494, NFκB1, and FBXO32 in ovarian cancer, which were tested by dual-luciferase reporter assay, RNA pull-down, RIP, and ChIP assay." (PMID 33585183, 2020). "Overexpression of LINC00494 elevated NFκB1 expression and enhanced cell migration, invasion and tumorigenesis, but additional overexpression of FBXO32 interfered with the tumorgenicity of ovarian cancer cells in vitro and in vivo." (PMID 33585183, 2020). "Topological analysis of the network reveals a set of 15 target genes that are regulated by SP3 or NFκB1 in normal cells, but by E2F1 in ovarian cancer." (PMID 22548828, 2012).